WNT5A (Wnt family member 5A)
Diseases named in the same sentence as WNT5A in open-access papers (continued):
Sharing a sentence is not in itself a finding about the gene and the disease.
breast carcinoma (continued). "The decrease in both expression level and activity of MMP9 in MDA MB468‐5A cells compared to control cells suggests that this gelatinase is involved in WNT‐5A‐modulated breast cancer cell migration and invasion." (PMID 23727359, 2013). "Ras homolog gene family member A (RhoA) is involved in Wnt-5a–induced migration of gastric and breast cancer cells." (PMID 24351810, 2013). "Phosphoinositide 3-kinase/protein kinase B (PI3K/Akt)-dependent phosphorylation of glycogen synthase kinase-3β (GSK3β) and RhoA activation regulate Wnt-5a–induced gastric cancer cell migration, in line with results for breast cancer cells." (PMID 24351810, 2013). "It has been shown that Wnt5a can have paracrine effects on the tumor microenvironment that can impact breast cancer progression." (PMID 23484019, 2013). "This information led us to next investigate the role of MMP9 in WNT‐5A‐impaired breast cancer cell migration and invasion." (PMID 23727359, 2013). "Microarray and RNA-seq performed in this report provide a comprehensive view of changes in gene expression elicited by over-expression of WNT5A in metastatic breast cancer cells." (PMID 23484019, 2013). "On the basis of these results, we conclude that WNT‐5A impairs breast cancer cell migration and invasion by increasing the activity of Cdc42, thereby decreasing ERK1/2 activity." (PMID 23727359, 2013). "Here we show that mis-expression of WNT5A in the highly metastatic breast cancer cell lines, 4T1 and MDA-MB-231, inhibits migration and metastasis as measured by transwell and a tail vein injection assays consistent with previous reports." (PMID 23484019, 2013). "In the present study we expand these findings by demonstrating that the ability of Wnt-5a to impair breast cancer cell migration is unrelated to the ER status of the tumor cells." (PMID 23990917, 2013). "Despite the fact that RhoGTPase Cdc42 is commonly associated with increased cell migration, we here show that recombinant WNT‐5A activates the Cdc42 in breast cancer cells (lines MDA‐MB468 and MDA‐MB231) in a time‐dependent manner." (PMID 23727359, 2013). "In this study, we report that WNT‐5A‐mediated activation of Cdc42 leads to decreased breast cancer cell migration and invasion via reduced ERK1/2 and MMP‐9 activities." (PMID 23727359, 2013). "Wnt-5a protein expression in primary tumors from unselected breast cancer patients has revealed a tumor suppressive function of the protein." (PMID 23990917, 2013). "An inverse correlation between malignant potential and WNT5A expression exists among several breast cancer cell lines." (PMID 23484019, 2013). "Here, we investigate for the first time the prognostic value of Wnt-5a expression in breast cancer tissue from a large cohort of premenopausal patients with comprehensive data on molecular subtypes and long-term outcome." (PMID 23990917, 2013). "In agreement, we here provide evidence that although WNT‐5A activates Cdc42, it causes a downstream decrease in ERK1/2 and MMP9 activities those results in impaired breast cancer cell migration and invasion." (PMID 23727359, 2013). "Second, we established a breast cancer cell line with stable expression of the WNT‐5A protein to study its long‐term effects." (PMID 23727359, 2013). "Taken together, these results lead us to conclude that WNT‐5A‐mediated impaired breast cancer cell migration and invasion is at least in part explained by a reduced release of MMP9." (PMID 23727359, 2013). "The proposal that WNT‐5A increases breast cancer cell migration is compatible with its capacity to increase Cdc42 activity in fibroblasts and non‐tumorigenic breast epithelial cells, since Cdc42 activity is commonly associated with increased cell migration." (PMID 23727359, 2013). "Other in vitro studies of breast cancer cells have led to the suggestion that WNT‐5A reduces the metastatic capability of invasive breast cancer by enhancing adhesion and decreasing migration." (PMID 23727359, 2013).
breast carcinoma (continued). "To gain information on how ERK1/2 can mediate its effect on breast cancer cell migration and invasion, we next investigated and demonstrated that WNT‐5A signaling and constitutively active Cdc42 both decreased matrix metalloproteinase 9 (MMP9) activity." (PMID 23727359, 2013). "We previously showed that WNT‐5A signaling inhibits migration and metastasis of breast cancer cells, and that patients with primary breast cancer in which WNT‐5A was expressed have a better prognosis." (PMID 23727359, 2013). "In human breast cancer tissue it has been shown that WNT‐5A protein expression accompanied prolonged disease‐free survival and overall survival." (PMID 23727359, 2013). "Other cell lines, including MCF-7 (derived from a breast carcinoma) or IMR-32 (derived from a neuroblastoma) express extremely low levels of either WNT5A isoform." (PMID 24260410, 2013). "To explore these discrepancies, we investigated the precise role of Cdc42 in WNT‐5A‐mediated signaling in breast cancer cells." (PMID 23727359, 2013). "Our results identify Wnt-5a as a potential independent marker of better prognosis, in premenopausal patients with ER+ breast cancer, including those in the luminal A subgroup." (PMID 23990917, 2013). "Here, we demonstrated for the first time that Wnt5a promotes the migration of breast cancer cells, and we report on the mechanisms whereby Wnt5a/PCP signaling regulates cell migration." (PMID 22655072, 2012). "MDA-MB-231 cells expressed lower levels of Wnt5a than breast cancer cell line MCF-7, which is consistent with the previous report." (PMID 22655072, 2012). "We showed here that Wnt5a activated Dvl2, Daam1 and RhoA, and promoted migration of breast cancer cells, which was, however, abolished by Secreted Frizzled-related protein 2 (sFRP2) pretreatment." (PMID 22655072, 2012). "These promiscuous viewpoints of Wnt5a in breast cancer progression led us to further elucidate the function of Wnt5a, and investigate the underlying mechanisms whereby cell migration is regulated." (PMID 22655072, 2012). "A primary observation in the present study is that Wnt5a induces the migration of MDA-MB-231 breast cancer cells, which lacks endogenous Wnt5a." (PMID 22655072, 2012). "In this study, we demonstrated that Wnt5a promotes MDA-MB-231 breast cancer cell migration by activating Dvl2/Daam1." (PMID 22655072, 2012). "In fact, recent data show that WNTs, and especially WNT-5A, signaling in microglia/macrophages, can promote invasiveness of breast cancer cells and especially their metastasis in the brain." (PMID 22647544, 2012). "Foxy5, a Wnt5a mimicking peptide, has been shown to impair cell motility of breast cancer cell lines with low endogenous Wnt5a levels and to significantly inhibit breast tumor metastasis to lung and liver in vivo." (PMID 23342259, 2012). "Taken together, we demonstrated for the first time that Wnt5a promotes breast cancer cell migration via Dvl2/Daam1/RhoA." (PMID 22655072, 2012). "In summary, we presented the first direct evidence that Wnt5a promotes breast cancer cell migration via Dvl2/Daam1/RhoA." (PMID 22655072, 2012). "First, Wnt5a expression was shown to positively correlate with disease-free survival, and Wnt5a blocks breast cancer cell invasion." (PMID 20507565, 2010). "The emerging view is that, in breast cancer, WNT5A has a suppressive effect, inhibiting migration and invasion of breast cancer cell lines." (PMID 21209903, 2010). "The key findings here are that TGF-β and Wnt5a antagonise Wnt/β-catenin signalling in mammary tissue and that loss of TGF-β or Wnt5a signalling can redirect the phenotype of mammary tumours to that resembling tumours induced by excessive Wnt/β-catenin." (PMID 19344510, 2009). "To determine the effects of alterations in TGF-β signalling (DNIIR) on Wnt5a expression during mammary tumour progression we used the previously characterised MMTV-neu and MMTV-PyVmT models of mouse mammary tumourigenesis." (PMID 19344510, 2009).
breast carcinoma (continued). "NFAT1, a transcription factor connected with breast cancer metastasis, is activated by Wnt-5a through a Ca2+ signaling pathway in human breast epithelial cells." (PMID 17316436, 2007). "To understand the mechanisms of regulation of Wnt5a, we investigated its expression in human normal and breast cancer cell lines." (PMID 9716023, 1998). "A decrease in Wnt5a and Wnt5b suppressed invasion in breast cancer." (PMID 40569965, 2025). "Wnt5a has been found to enhance breast cancer cell migration and invasion." (PMID 40569965, 2025). "With regard to calcium signaling, Wnt5a exhibits tumor suppressor function in several tissue and tumor types, such as neuroblastoma, esophageal squamous cell carcinoma, acute myeloid lymphoma, breast cancer, thyroid carcinoma, and colon carcinoma." (PMID 39123414, 2024). "Additionally, several studies have demonstrated the frequent detection of increased levels of Wnt5a in the serum of patients with breast cancer, which exhibited a strong correlation with microvessel density in breast tumor tissues." (PMID 38273859, 2023). "Although the expression of the WNT5A protein in hepatocellular carcinoma and breast cancer has been shown to be regulated at the translational level, the reduction in WNT5A protein expression in colon cancer tissue has been shown to be due to methylation of the WNT5A promoter." (PMID 37998393, 2023). "The LDOC2 gene regulates WNT5A expression, which promotes breast cancer cell migration." (PMID 37761960, 2023). "Supporting these results, in tissue microarrays of breast cancer samples, a correlation between WNT5A expression in tumor cells and the percentage of M2 macrophages could be shown." (PMID 36982422, 2023). "Expression of the active form of WNT5A was only detected in HS578T-Hyg breast cancer cells." (PMID 38139138, 2023). "In contrast, WNT5a inhibits the progression of breast cancer and liver cancer." (PMID 37486552, 2023). "Finally, we found that in the MDA-MB-231 breast cancer cell model for Wnt5a signaling, OTULIN loss led to deficits in Wnt5a-induced filopodia extension and redistribution of transfected HA-VANGL2." (PMID 37589075, 2023). "Notably, Wnt5a is overexpressed specifically in basal breast cancer cell lines (MDA-MB-231 and BCap-37), which harbor a mesenchymal phenotype and a high proportion of CSCs." (PMID 37492224, 2023). "Further analysis identified WNT5A as an essential downstream gene of ATBF1 in breast cancer cells." (PMID 36476423, 2022). "Other studies suggest that breast cancer-derived exosomes could increase the expression of Wnt5a in macrophages, and then transfer Wnt5a to tumor cells via exosomes to improve the invasive ability of tumor cells." (PMID 35741075, 2022). "We also detected the expression of WNT5A in breast cancer patients." (PMID 36476423, 2022). "Thus, this evidence supports the Wnt5a-dependent angiogenesis role of stromal FOSL2 in breast cancer." (PMID 33754039, 2021). "Moreover, we unveiled the clinical significance of the FOSL2/Wnt5a axis to gain insights into its pro-angiogenic function in the development and progression of breast carcinoma, suggesting potential novel therapeutic strategies for anti-angiogenic therapy." (PMID 33754039, 2021). "However, the opposite has also been shown: WNT5A is higher in breast carcinomas and induces tumorigenicity in breast cancer." (PMID 34017835, 2021). "In addition, a high level of Wnt5a was commonly detected in the serum of breast cancer patients and closely correlated with microvessel density in breast tumor tissues, suggesting a promising clinical value of Wnt5a for breast cancer diagnostics." (PMID 33754039, 2021). "Our findings provide important evidence for its oncogenic role in the breast tumor microenvironment, which suggests that targeting Wnt5a in the breast TME may provide a potential option for antiangiogenesis therapy in breast cancer." (PMID 33754039, 2021).
breast carcinoma (continued). "Reduced protein levels of the non-canonical Wnt ligand, Wnt5a, is observed in 45–75% of breast cancer patients and is associated with poor prognosis including early relapse and reduced disease free-survival." (PMID 33805424, 2021). "Considering the ambiguous role of WNT5A which has been described to act both as an oncogene as well as a tumor suppressor in breast cancer, it is still unclear whether other WNT ligands exist that can activate ROR2 signaling." (PMID 34911552, 2021). "In breast cancer, the respectable evidence supports that Wnt5a has oncogenic activity." (PMID 33754039, 2021). "Interestingly, among DEGs, a relevant number of genes involved in oxidative metabolism (e.g. GSTP1, CYP4Z1, AKR1B10) and in different pathways affecting breast cancer behavior (WNT5A), was observed." (PMID 33863935, 2021). "In addition, treating human MCF7 breast cancer cells with recombinant Wnt5a led to a significant reduction in rRNA synthesis as measured by 47S pre-rRNA levels, cellular proliferation, and decreased nucleolar area." (PMID 33805424, 2021). "Previous studies reported that 45% to 75% of breast cancer patients presented negative or lower expression of the WNT5A protein, which has been associated with disease progression and metastasis, and a poor recurrence-free survival." (PMID 34572445, 2021). "FZD2 and its ligands Wnt5a/b (Wnt signaling pathway) were elevated in many cancers including breast cancer, and their expression correlated with epithelial–mesenchymal transition (EMT), which is a process that allows cancer cells to infiltrate surrounding tissues and metastasize to distant sites." (PMID 32053966, 2020). "Nonetheless, it has been reported that Wnt5a is lost in breast cancer." (PMID 33234169, 2020). "Previously, it was reported that SMARCD3 could stimulate EMT of breast cancer cells through upregulating WNT5A expression." (PMID 33125346, 2020). "Additionally, miR-374a activates Wnt/β-catenin signaling by directly targeting WIF1, PTEN, and WNT5A, thereby promoting breast cancer metastasis." (PMID 32674274, 2020). "Another study provided evidence that Wnt5a represses ribosomal RNA (rRNA) synthesis by promoting DVL-1 accumulation in nucleolus of breast cancer cells, where nucleolar DVL-1 releases Pol I transcription activator and SIRT7 from rDNA loci, thereby inhibiting tumor growth." (PMID 33126517, 2020). "Therefore, using a small WNT5A-mimicking peptide Foxy5 has been suggested as a future anti-metastatic treatment strategy for breast cancer patients." (PMID 32824207, 2020). "Moreover, TGF-β directly regulates the expression of Wnt5a in breast cancer, and Wnt5a acts as an effector of TGF-β actions in the branching of mammary gland development and cancer." (PMID 33158118, 2020). "Our study has revealed that NAC dramatically alters epigenetic heterogeneity in breast cancer and induces convergent hypomethylation of stem cell quiescence-associated genes, ALDH1L1, HOPX, WNT5A and SOX9, which can potentially be developed as therapeutic targets or biomarkers for chemoresistance." (PMID 30774927, 2019). "We observed a high correlation between Wnt5a and ER expression in breast cancers." (PMID 29765514, 2018). "The role of Wnt5a expression in breast cancer remains elusive." (PMID 29765514, 2018). "Thus, in order to understand the mechanism whereby reduced expression of the WNT5A protein leads to breast cancer progression, one has to understand how WNT5A signaling affects breast cancer cell behavior." (PMID 30171384, 2018). "Interestingly, diacetylation of TWIST by KAT5 resulted in an active TWIST complex at the Wnt5a promoter in basal-like breast cancer." (PMID 29449840, 2018). "However, for these experiments, the authors have used a non-invasive luminal breast cancer cell line (MCF-7) that normally has an endogenous WNT5A expression." (PMID 30171384, 2018). "However, the function of Wnt5a has been reported as both a tumor suppressor and a tumor promotor in breast cancer." (PMID 29765514, 2018).
breast carcinoma (continued). "Our investigation of breast cancer tissues also revealed that Wnt5a expression correlates with ALCAM expression in ER-positive breast cancers, indicating that Wnt5a-positive/ALCAM-positive breast cancers form a biologically distinct subgroup of ER-positive breast cancers." (PMID 29765514, 2018). "Whether Wnt5a expression in breast cancer correlates with pathological factors such as lymph node metastasis and grade is unknown." (PMID 29765514, 2018). "The concept that WNT5A acts as a suppressor of breast cancer progression is also supported by the results of numerous in vitro studies, indicating that WNT5A primarily reduces the migratory and invasive capacities of breast cancer cells." (PMID 30171384, 2018). "Interestingly, the WNT5A triggered phosphorylation of DRAPP-32 was shown to impair MCF7 breast cancer cell migration." (PMID 30171384, 2018). "As the expression of WNT5A protein predicts longer disease-free survival in breast cancer patients, its metastasis-suppressing activity might at least in part be due to increased DDR1-dependent cell adhesion and decreased migration." (PMID 30171384, 2018). "In breast cancer, co-expression of Wnt ligands, including Wnt3, Wnt4, Wnt5a, and Wnt7a, leads to the activation of Wnt pathway, while in colorectal cancer, mutation or loss function of the APC gene or protein is more likely to be the reason for Wnt pathway activation." (PMID 29986466, 2018). "Interestingly, all patients with recurrent breast cancer in this study had bone metastasis, suggesting that Wnt5a plays a role in bone metastasis in breast cancer." (PMID 29765514, 2018). "Using breast cancer cells, the authors demonstrated that WNT5A signaling through segment polarity protein dishevelled homolog (DVL1) represses ribosomal DNA gene transcription and generates a chromatic state resulting in less transcription of rDNA by RNA polymerase I." (PMID 30171384, 2018). "We investigated the significance of Wnt5a expression in breast cancer." (PMID 29765514, 2018). "However, the development of WNT5A as a therapeutic target for the treatment of breast cancer patients has been impeded by the fact that WNT5A has a specific heparin sulfate-binding domain that will hinder its distribution in vivo." (PMID 30171384, 2018). "In breast cancer, WNT5A has been shown to be regulated at the post-transcriptional level via HuR, a member of embryonic lethal abnormal vision (ELAV)-like protein family that binds to evolutionary conserved AU-rich motifs in the untranslated region of its mRNA and suppresses translation." (PMID 30171384, 2018). "Whether and to what extent WNT5A signaling also affects breast cancer cell proliferation, as suggested above, needs further investigation." (PMID 30171384, 2018). "Another important mechanism that could contribute to the anti-invasive property of WNT5A signaling in breast cancer is the activation status of the transcription factor nuclear factor associated with T cells (NFAT)." (PMID 30171384, 2018). "The data was further validated by demonstrating reduced LEF/TCF reporter activity in WNT5A-expressing breast cancer cells, proposing that WNT5A not only suppresses β-catenin protein expression but also inhibits its downstream transcriptional activity in breast cancer cells." (PMID 29069720, 2017). "Moreover, significant inhibition of LEF/TCF reporter activity was found in MDA-MB-468-5A cells compared to MDA-MB-468-EV cells, thereby indicating that WNT5A signaling impairs β-catenin signaling in breast cancer cells." (PMID 29069720, 2017). "Owing to the synchronous highly expression pattern of Wnt5a in breast cancer, gastric cancer, non-small-cell lung cancer, prostate cancer, we predict that Wnt5a and ROR2 may act as co-effector in certain specific tumors." (PMID 29213214, 2017).